MYD88 (MYD88 innate immune signal transduction adaptor)
Diseases named in the same sentence as MYD88 in open-access papers (continued):
Sharing a sentence is not in itself a finding about the gene and the disease.
colorectal cancer (47 papers, 2009 to 2025). A primary or metastatic malignant neoplasm that affects the colon or rectum. "A similar study on TRUC mouse models (lacking T-bet and RAG2 genes) showed the importance of commensals in inflammatory responses using the MyD88-independent pathway that led to the development of colitis-associated colorectal cancer (caCRC)." (PMID 40927726, 2025). "As demonstrated by the case of MYD88, where MYD88 inactivation suppresses cancer but may potentially result in colorectal cancer (CRC) linked to the damaged epithelium, TLRs also play a protective function." (PMID 37706437, 2023). "TLR4/MyD88/NF-κB signaling pathway is a well-known pathway related to immune inflammatory responses and its activation is associated with multiple diseases, such as knee osteoarthritis, ulcerative colitis, and colorectal cancer." (PMID 31885500, 2019). "Toll-like receptor 4 (TLR4) and myeloid differentiation factor 88 (MyD88) signaling play a critical role in colorectal cancer (CRC) development." (PMID 40703545, 2025). "Our study found that MyD88 methylation in mice infected with T. spiralis aligned with humans exposed to H. pylori–triggered chronic inflammation and colorectal cancer." (PMID 39905552, 2025). "Our comprehensive analysis of TLR4/MyD88 pathway in colorectal cancer reveals three key findings that advance our understanding of inflammatory signaling in colorectal carcinogenesis." (PMID 40703545, 2025). "Our study revealed distinct expression patterns of TLR4/MyD88 in colorectal cancer compared to adenomas, with several important implications for understanding CRC pathogenesis." (PMID 40703545, 2025). "In ovarian and colorectal cancers, sustained MyD88 activation promotes increased secretion of IL-10 and TGF-β, which suppresses effector T cell function and expands Tregs." (PMID 41488647, 2025). "The MyD88/NF-kB signaling axis is a central pathway in regulating inflammatory responses and tumor progression in colorectal cancer." (PMID 40143078, 2025). "This study establishes three key findings regarding TLR4/MyD88 pathway alterations in colorectal cancer." (PMID 40703545, 2025). "As proof, RBM15 knockdown suppressed colorectal cancer development by regulating the m6A levels in MYD88 mRNA." (PMID 39023191, 2024). "A study showed that Myd88 silencing significantly inhibited the growth and invasion of colorectal cancer cells SW480 and HCT116." (PMID 37953776, 2023). "MyD88 is highly expressed in colorectal cancer and plays a predominant role in promoting colorectal cancer cell proliferation, invasion and metastasis." (PMID 37630236, 2023). "Meanwhile, low levels of MYD88 from the cohort of colorectal cancer was consistent with our results." (PMID 37456890, 2023). "While, some studies reported that the MyD88 signaling possesses the protective role in the malignant transformation of intestinal inflammatory conditions to colorectal cancer." (PMID 38110638, 2023). "The knocking down of MyD88 reduced the activity of NF-kB and AP-1 pathways that resulted in the inhibition of colorectal cancer progression." (PMID 37630236, 2023). "Studies had suggested that MYD88 knockdown repressed LPS-induced inflammation in colorectal cancer cells." (PMID 35609334, 2022). "As a potential anti-inflammatory target, BMI1 regulates invasion and EMT of colorectal cancer cells via TLR4/MD-2 MyD88 complex-mediated NF-κB signaling pathway." (PMID 33927214, 2021). "Fusobacterium nucleatum targets TLR4 and MYD88 innate immune signaling and specific microRNAs to activate the autophagy pathway and alter the chemotherapeutic response in colorectal cancer." (PMID 33854588, 2021). "Previous studies demonstrated that MYD88 has an important function in tumorigenesis, and high levels of MYD88 correlate with poor prognosis in patients with colorectal cancers." (PMID 24527027, 2014). "Their findings suggest that TLR4/MyD88 signaling promotes colorectal cancer progression by contributing to liver metastasis." (PMID 22985132, 2012).
colorectal cancer (continued). "To demonstrate the role of TLR4 signalling in colon tumourigenesis, we examined the expression of TLR4 and myeloid differentiation factor 88 (MyD88) in colorectal cancer (CRC)." (PMID 20145615, 2010). "Our findings suggest potential future research directions for TLR4/MyD88 pathway modulation in colorectal cancer, though extensive functional validation and clinical studies would be required before any therapeutic applications could be considered." (PMID 40703545, 2025). "Furthermore, it has been reported that RBM15-mediated m6A modification of MyD88 mRNA sustains MyD88 stability and accelerates the proliferative and invasive abilities of colorectal cancer cells." (PMID 40883807, 2025). "Meanwhile, in a preclinical study of colorectal cancer, researchers found that silencing MyD88 in SW480 (human colon adenocarcinoma cells) and HCT116 (human colon cancer cells) interferes with the MyD88/NF-κB/AP-1 signaling pathway and significantly inhibits cancer cell growth and invasion." (PMID 38785969, 2024). "Bmi-1 may also regulate the TLR4/MD2/MyD88 complex-mediated NF-κB signaling pathway to participate in colorectal cancer cell EMT." (PMID 35897796, 2022). "Previous study revealed that MYD88 might promote tumor cell survival through IRAK-mediated NF-κB signaling in colorectal carcinoma cells." (PMID 33898320, 2021). "Furthermore, previous studies have demonstrated that elevated RBM15 could accelerate colorectal cancer cell growth and metastasis through m6A modification of MyD88 and KLF1 mRNA." (PMID 40883807, 2025). "In addition, the MyD88-dependent pathway of LPS signaling has been suggested to play a potential prognostic role for tumor malignancy in colorectal cancer development, and forced MyD88 expression has been reported to induce the production of inflammatory cytokines such as IL-6 and IL-8." (PMID 25691060, 2015). "For example, F. nucleatum activates autophagy-related pathways in colorectal cancer through modulation of TLR4 and MYD88 innate signaling, along with certain miRNAs which subsequently promote chemoresistance." (PMID 33197886, 2020). "Via binding to TLR4 on colorectal cancer cells, Fusobacterium nucleatum activated the TLR4/MYD88 innate immune signaling pathway and miRNA-18a and miRNA-4802 were downregulated sequentially, which resulted in ULK1 and ATK7 expression." (PMID 30374420, 2018). "One such bacterium is Fusobacterium nucleatum which is associated with adverse prognosis and recurrence after chemotherapy (using 5-fluorouracil and oxaliplatin) for colorectal cancer (CRC), which influences molecules such as TLR4 and MYD88, and triggers microRNAs and autophagy mechanisms." (PMID 40927726, 2025). "Fusobacterium nucleatum has been detected in both colorectal cancer tissues and fecal samples, influencing treatment responses by targeting Toll-like receptor 4 (TLR4) and MyD88 immune pathways and specific microRNAs to activate autophagy, thus serving as a biomarker for colorectal cancer." (PMID 39545038, 2024). "Moreover, Bmi-1 promote colorectal cancer migration and EMT in an inflammatory microenvironment by regulating TLR4/MD2/MyD88 complex-mediated NF-κB signaling pathway." (PMID 35897796, 2022). "Yu and colleagues have also shown that, in colorectal cancer models, Fusobacterium nucleatum may activate TLR4 and MyD88 immune signalling pathways, as well as downregulation of specific microRNAs in order to activate the autophagy pathway and reduce cell apoptosis induced by oxaliplatin and 5-FU." (PMID 35205769, 2022).
liver fibrosis (47 papers, 2010 to 2025). "A lower degree of liver fibrosis was documented in studies of carbon tetrachloride- or bile duct ligation-induced liver fibrosis in TLR4-mutant mice along with mutations in MyD88, CD14, TRIF and LBP." (PMID 39201329, 2024). "Gut-derived LPS can stimulate TLR4 of quiescent HSCs and activate these cells in a MyD88-NF-κB-dependent manner, thus causing profibrogenic transformation and accelerating liver fibrosis." (PMID 37408838, 2022). "In this study, we found that MyD88 deficiency in HSCs attenuates liver fibrosis and inflammatory cell infiltration in CCl4-induced mice." (PMID 35484116, 2022). "MyD88 deficiency in qHSCs or aHSCs attenuated liver fibrosis in mice and inhibited α-SMA-positive cell activation." (PMID 35484116, 2022). "In this study, we found that MyD88 deficiency in myeloid cells attenuated CCl4-induced liver fibrosis." (PMID 34830293, 2021). "MyD88 deficiency in myeloid cells attenuated liver fibrosis in mice and decreased inflammatory cell infiltration." (PMID 34830293, 2021). "In experimental animal models, attenuation of either liver fibrosis or liver inflammation was associated by reduced MyD88 expression in either nonalcoholic steatohepatitis related hepatic fibrosis or chronic alcohol fed rats respectively." (PMID 27135246, 2016). "MyD88 deficiency significantly reduces liver fibrosis and decreases eosinophil percentage in vivo." (PMID 34830293, 2021). "Inhibition of inflammasome activation may be an important cause of attenuated liver fibrosis in mice with myeloid-specific deletion of MyD88." (PMID 34830293, 2021). "In addition, liver endothelial cells (LECs) can express TLR4 signaling to regulate angiogenesis through MyD88 pathway, linked to the development of liver fibrosis." (PMID 25153081, 2014). "Otherwise, Astragalus polysaccharide alleviated alcoholic-induced hepatic fibrosis by inhibiting TLR4/JNK/NF-κB/MyD88 pathway." (PMID 40771890, 2025). "Macrophages are induced to undergo M1-type polarization by MyD88 in hepatic stellate cells, which can enhance liver fibrosis." (PMID 40244063, 2025). "For example, HBsAg can stimulate RAW264.7 through the TLR2/MyD88/NF-κB signaling pathway, enhancing the mobility, proliferation, and contraction of HSCs, thereby exacerbating liver fibrosis." (PMID 39199394, 2024). "These cells further activated HSCs via CX3CR1/MyD88/NF-κB pathway and consequently promoted liver fibrosis and MAFLD progression." (PMID 38627387, 2024). "FSE can inhibit the expression of inflammatory factors and fibrotic cytokines, reduce liver injury, and inhibit the development of liver fibrosis through TLR4/MyD88/NF-κB and TGF-β/smads signaling pathways." (PMID 39359922, 2024). "The results indicate that CPhGs played an anti-hepatic fibrosis role via inhibiting expression of the LPS-TLR4/MyD88/NF-κB signaling pathway." (PMID 39338312, 2024). "The oxidative stress condition provokes the inflammation and recruitment of Cx3cr1+Ccr2+MyD88+ Mo-macs that drive liver fibrosis via CX3CR1/MyD88/NF-κB/S100A pathway." (PMID 38684673, 2024). "Thirdly, the authors proposed targeting Cx3cr1+Ccr2+MyD88+ Mo-macs-mediated liver fibrosis, which showed improvement upon treatment with the MyD88 inhibitor, ST2825, in Mettl14-KO mice." (PMID 38684673, 2024). "We also found MyD88 in macrophages enhance liver fibrosis by activation of NLRP3 inflammasome in HSCs.In addition, MyD88 expression was crucial for HSC activation in vitro." (PMID 35484116, 2022). "Our results showed that the MyD88 signaling pathway was activated in HSCs and promoted CCl4-induced liver fibrosis, which is consistent with previous studies that LPS/TLR4/MyD88 signaling is involved in the activation of HSCs during liver injury." (PMID 35484116, 2022). "In the present study, we showed that HSC specific MyD88 deletion inhibited the activation of HSCs and attenuated CCl4-induced liver fibrosis." (PMID 35484116, 2022).
liver fibrosis (continued). "A mouse model of liver fibrosis suggests that MyD88 signaling in activated HSCs promotes macrophage M1 polarization in a CXCL10/CXCR3-dependent manner, thus promoting liver fibrosis and inflammation." (PMID 37408838, 2022). "In conclusion, our results indicated that deletion of MyD88 in HSCs significantly attenuated liver fibrosis and liver inflammatory response." (PMID 35484116, 2022). "The results suggested that CIH induced liver fibrosis by TLR4/MyD88/MAPK/NF-kB signaling pathways in DIO mice." (PMID 36187780, 2022). "To identify the role of MyD88 in HSCs in liver fibrosis, we treated GFAPMyD88−/−−, SMAMyD88−/−− mice and control littermates with CCl4." (PMID 35484116, 2022). "The profibrotic role of B cells in the CCl4-induced liver fibrosis model depends on the myeloid differentiation primary response 88 (MYD88), which is indispensable for proper activation and proinflammatory cytokine production." (PMID 35747688, 2022). "During the formation of liver fibrosis, the protein expression of MyD88 in hepatic stellate cells increased significantly, suggesting that MyD88 plays an important role on liver fibrosis." (PMID 36579341, 2022). "Recently, it has been reported that deletion of MyD88 in B cells attenuated CCl4-induced liver fibrosis." (PMID 35484116, 2022). "The obtained results suggest that MyD88 is significantly upregulated in macrophages during the progression of liver fibrosis." (PMID 34830293, 2021). "In this study, we first reported the myeloid cell-specific role of MyD88 signaling in liver fibrosis." (PMID 34830293, 2021). "Deletion of MyD88 in myeloid cells attenuated liver fibrosis by reducing inflammatory cell infiltration." (PMID 34830293, 2021). "Targeted deletion of B-cell-intrinsic MyD88 signaling resulted in reduced infiltration of migratory CD11c+ dendritic cells and Ly6C+ monocytes and hence reduced liver fibrosis." (PMID 34830293, 2021). "In conclusion, this study demonstrated that chronic administration of eritoran significantly attenuated liver inflammation and fibrosis in the FFD- and CCl4-indued liver fibrosis models by suppressing the MyD88–NF-κB pathway in the liver, HSCs and KCs." (PMID 34205789, 2021). "In this study, the role of MyD88 signaling in macrophages in the pathogenesis of liver fibrosis was investigated." (PMID 34830293, 2021). "The signal adaptor MyD88 of Toll-like receptor (TLR) signaling is involved during the progression of liver fibrosis." (PMID 34830293, 2021). "In conclusion, our study demonstrated that MyD88 in macrophages promoted the development of liver fibrosis via activating NLRP3 inflammasome in HSCs." (PMID 34830293, 2021). "Hypoxia has been recognized as an inducer of the activation of the TLR4/MyD88/NF-κB pathway in hepatic ischemia/reperfusion injury and liver fibrosis." (PMID 33195243, 2020). "The TLR4-triggered MyD88 pathway was found to be crucial to hepatic fibrosis by potentiating pro-fibrotic TGF-β1 signalling." (PMID 29247242, 2017). "LPS regulated TGFβ1-induced signals from HSC in TLR4/MyD88 in a dependent manner, thus modulating liver fibrosis in NASH." (PMID 23441159, 2013). "Ghrelin appears to ameliorate liver fibrosis formation, indicating that inhibiting the MyD88 signaling pathway to upregulate Ghrelin expression may collaboratively reduce the occurrence of liver fibrosis during E. multilocularis infection." (PMID 39749332, 2024). "Inhibiting the MyD88 signaling pathway and upregulating Ghrelin expression might collaboratively mitigate the development of liver fibrosis during E. multilocularis infection." (PMID 39749332, 2024). "However, due to its wide expression, the cell-type specific contribution of MyD88-mediated signaling to liver fibrosis is still unclear." (PMID 35484116, 2022).
liver fibrosis (continued). "Consistent with the results of previous animal studies, the investigation of the cell insulin signaling pathway suggested that the H-L + HFD-induced liver fibrosis was mediated by gut microbiota through disruption of the gut barrier TLR4/MYD88 and liver IRS1/Akt/mTOR signaling pathways." (PMID 36204709, 2022). "MyD88 expression in liver fibrosis was further confirmed by Western blot analysis." (PMID 35484116, 2022). "In this study, we first demonstrated the role of MyD88 signaling in HSCs in liver fibrosis." (PMID 35484116, 2022). "In addition, upregulation of MyD88 during fibrosis progression was also found in thioacetamide (TAA) induced liver fibrosis model, which based on C57BL/6 mice treated with TAA." (PMID 35484116, 2022). "However, far less is known about the specific effects of MyD88 signaling in both qHSCs and aHSCs in the progress of liver fibrosis." (PMID 35484116, 2022). "Thus, MyD88 signaling in HSCs crucially contributes to liver fibrosis and provides a promising therapeutic target for the prevention and treatment of liver fibrosis." (PMID 35484116, 2022). "There are increasing evidence that TLRs and MyD88 play important roles in liver fibrosis." (PMID 35484116, 2022). "Our results demonstrated that MyD88 in myeloid cellsenhanced hepatic fibrosis." (PMID 34830293, 2021). "Therefore, we tested the expression levels of HMGB1, TLR4, Myd88, and NF-κB p65, which are the key targets of this signaling pathway in liver fibrosis rats." (PMID 33790974, 2021). "We investigated whether BGH can prevent hepatic fibrosis and tubulointerstitial fibrosis by downregulating the innate immune MyD88–NF-κB–IKKβ pathway." (PMID 34829154, 2021). "In conclusion, TLR7 and MyD88 are possible candidates as biomarkers for the progression of HCV-induced liver fibrosis and/ or targets for therapeutic intervention to halt worsening of the clinical course of HCV chronic infection in patients who are uneligible or resistant to DAAs treatment." (PMID 27135246, 2016). "Disruption of TLR9, MyD88, or IL-1β signaling significantly attenuates liver fibrosis." (PMID 24340043, 2013). "Thus, MyD88 in HSCs may represent a potential candidate for the prevention and therapy of liver fibrosis." (PMID 35484116, 2022). "Inhibition of MyD88 activation in HSCs may be a potential therapeutic target for liver fibrosis." (PMID 35484116, 2022). "Thus, MyD88 may represent a potential candidate target for the prevention and treatment of liver fibrosis." (PMID 34830293, 2021). "Thus, MyD88 in macrophages may represent a potential candidate for the prevention and therapy of liver fibrosis." (PMID 34830293, 2021). "Our study shows that the TLR4, MyD88, p-IκB, and p-NF-κB protein expressions levels were considerably elevated in rats with BSA-induced liver fibrosis compared to the controls, while the CPhGs intervention effectively inhibited these changes (p < 0.05)." (PMID 39338312, 2024). "In HSCs, TLRs-MyD88 activates downstream signaling molecules, such as P38 and JNK, promoting liver fibrosis." (PMID 39105051, 2024). "The TLR2/MyD88/NF-κB signaling pathway, mediated by TLR2, is crucial for macrophage activation and stellate cell promotion, contributing to liver fibrosis progression." (PMID 39199394, 2024). "The signal adapter MyD88, an essential component of TLR signaling, plays an important role in liver fibrosis." (PMID 35484116, 2022). "Here, our results indicated that MyD88 in macrophages activates HSCs through CXCL2 secretion and promotes liver fibrosis." (PMID 34830293, 2021). "The present study also showed that both liver fibrosis and chronic psychological stress could lead to LPS-TLR4 pathway depend on MyD88 be activated." (PMID 36579341, 2022). "To evaluate the effect of MyD88 signaling in myeloid cells in liver fibrosis, we generated mice lacking MyD88 in myeloid cells (MyD88Lyz-KO mice)." (PMID 34830293, 2021).